TRMT2A (tRNA methyltransferase 2A)
Description:
S-adenosyl-L-methionine-dependent methyltransferase that catalyzes the formation of 5-methyl-uridine in tRNAs and some mRNAs. Mainly catalyzes the methylation of uridine at position 54 (m5U54) in cytosolic tRNAs. Also able to mediate the formation of 5-methyl-uridine in some mRNAs.
Synonyms: HTF9C
Tractability: PROTAC: ubiquitination databases record sites on it; its protein half-life has been measured.
Gene: Protein-coding gene on chromosome 22 (20,111,875 to 20,117,392, reverse strand). Ensembl gene ENSG00000099899.
Subcellular location: Cytoplasm, cytosol
Subcellular location (Human Protein Atlas): Cytosol; Nucleoplasm
Gene Ontology:
Molecular function: C-methyltransferase activity; protein binding; RNA binding; tRNA (uracil(54)-C5)-methyltransferase activity, S-adenosyl methionine-dependent; nucleic acid binding; RNA methyltransferase activity
Biological process: RNA processing
Cellular component: cytosol
Genetic constraint (gnomAD): Loss-of-function variants: 61 observed, 55.55 expected, observed/expected ratio (o/e) 1.1, 90% interval 0.89 to 1.36. The upper end of that interval is the gene's LOEUF score, 1.36, which puts it in group 5 of 6, group 1 being the genes least tolerant of losing a copy. Missense variants: 863 observed, 829.43 expected, observed/expected ratio (o/e) 1.04, 90% interval 0.98 to 1.1. Synonymous variants: 403 observed, 349.12 expected, observed/expected ratio (o/e) 1.15, 90% interval 1.06 to 1.25.
Homologues: Orthologues: chimpanzee TRMT2A (99% identical), macaque TRMT2A (97% identical), guinea pig TRMT2A (87% identical), dog TRMT2A (86% identical), pig TRMT2A (84% identical), mouse Trmt2a (82% identical), rat Trmt2a (82% identical), tropical clawed frog trmt2a (59% identical), zebrafish trmt2a (54% identical), Drosophila melanogaster CG3808 (35% identical), Caenorhabditis elegans trm-2A (28% identical). Paralogues in human: TRMT2B (30% identical).
Diseases named in the same sentence as TRMT2A in open-access papers:
TRMT2A is named in the same sentence as 5 diseases in open-access papers, as found by Europe PMC text mining. Sharing a sentence is not in itself a finding about the gene and the disease. The quoted sentences say what the papers report.
breast carcinoma (4 papers, 2010 to 2023). "TRMT2A gene encodes a protein characterized as a biomarker of increased risk of recurrence in HER2 + breast cancer patients." (PMID 37347079, 2023). "Studies from three independent single institution cohorts support TRMT2A protein expression as a biomarker of increased risk of recurrence in HER2+ breast cancer patients." (PMID 20307320, 2010). "Interestingly, TRMT2A has been recently identified as biomarker of increased risk of recurrence in HER2+ breast cancer patients." (PMID 33799331, 2021). "For example, several tRNA modification genes have been found to be significantly dysregulated in various cancers and some have even been used as specific biomarkers, for example, TRMT2A in breast cancer." (PMID 26416026, 2015). "In the light of our findings, it is reasonable to speculate that TRMT2A may be a putative therapeutic target to modulate HER2+ breast cancer recurrence." (PMID 33799331, 2021). "Our data suggests that HER2+/TRMT2A+ breast cancers are more likely to recur treated with traditional cytotoxic therapy alone and therefore more aggressive treatment in the adjuvant setting may need to be considered for these patients, regardless of the other conventional risk factors." (PMID 20307320, 2010).
cognitive decline (1 paper, 2025). "Unlike GALNT2 and TRMT2A, whose evidence of involvement in AD are limited, MFGE8 (a.k.a. medin) is strongly linked to AD, as it interacts directly with amyloid-β to promote its aggregation and it is associated with cognitive decline." (PMID 40602528, 2025).
COVID-19 (1 paper, 2023). A disease caused by infection with severe acute respiratory syndrome coronavirus 2. "Understanding the biology and functional significance of the four obtained genes (TRMT2A, EXOSC5, REXO2, and MESD) provides insights into the molecular processes associated with disease severity in COVID-19." (PMID 37347079, 2023).
tumor (4 papers, 2010 to 2024). "When present in tumor cases, TRMT2A protein expression typically demonstrates a homogenous cytoplasmic pattern with some additional staining of nuclei." (PMID 20307320, 2010). "TRMT2A stained cases showed a strong uniform granular cytoplasmic staining of tumor cells." (PMID 20307320, 2010). "Given TRMT2A's strong prognostic association in HER2 expressing patients and its periodic expression during the cell cycle, it is interesting to speculate that TRMT2A over-expression may reflect tumor cells driven by an activated HER2 pathway towards aggressive growth." (PMID 20307320, 2010). "By multivariable analysis TRMT2A was independent of tumor size, nodal status and grade in both the CCIH and RPCI cohorts." (PMID 20307320, 2010).
TRMT2A also shares sentences with these, for which no sentence is quoted: cancer (2 papers).